MDM2 (MDM2 proto-oncogene)
Diseases named in the same sentence as MDM2 in open-access papers (continued):
Sharing a sentence is not in itself a finding about the gene and the disease.
cancer (continued). "Previous studies have revealed MDM2 promoter P2 SNP variants like SNP309T > G and SNP285G > C to modulate gene transcription and affect cancer risk." (PMID 28158999, 2017). "Together, either IL-6 exposure or continuous lenalidomide treatment enhanced A-to-I editing of GLI1 as well as other cancer-associated associated transcripts, including APOBEC3D, AZIN1, and MDM2." (PMID 29203771, 2017). "A better understanding of the regulation of Mdm2 is essential to developing novel and more effective cancer therapeutic strategies that can target Mdm2 in cancer cells while leaving normal cells intact." (PMID 28218667, 2017). "MDM2 is overexpressed in a variety of different types of cancers which is due to its gene amplification or regulation at the protein level." (PMID 29065514, 2017). "Although MDM2 is an oncogene that is overexpressed in various types of cancers, it is also expressed in Hacat in a lower level, which makes the Hacat cells were much less sensitive to estradiol(10×10-13M) compared to that of GLL19 and A375 cell lines." (PMID 28035066, 2017).
cancer (continued). "LicA treatment decreased the expression of MDM2, Cyclin B1, Cdc2 and Cdc25C in H460 and A549 cancer cell lines." (PMID 28805696, 2017). "There are a number of pre-clinical studies demonstrating the promise of targeting MDM2 via PPIs in cancers with either high endogenous MDM2 expression or targeting MDM2 following induction of MDM2 expression via DNA damaging agents." (PMID 29065514, 2017). "The identification of a common gene regulatory network governed by EZH2 and Mdm2 in primary cells, stem cells, and cancer cells raised the question of an interactive relationship between the two proteins." (PMID 27927750, 2017). "In cancer, the mouse double minute 2 (MDM2) is an oncoprotein that contributes to the promotion of cell growth, survival, invasion, and therapeutic resistance." (PMID 29065514, 2017). "Due to the fact that immunoblot experiments were performed on human cancer cell line, we were detecting Mdm2 human analogue – Hdm2." (PMID 27526774, 2016).
cancer (continued). "The human homolog of mouse double minute 2 (MDM2) is an oncoprotein overexpressed in different types of malignant cancers, due to gene amplification or the SNP309 polymorphism in the promoter region of MDM2." (PMID 27129163, 2016). "The association between MDM2 SNP285 polymorphism and cancer risk has been investigated by several research groups, but the conclusions were inconsistent." (PMID 27890964, 2016). "MDM2 remains of interest because agents targeting it, such as nutlins and in particular nutlin-3, are being investigated as anti-cancer drugs." (PMID 26754547, 2016). "SAR405838 is the latest oral MDM2 antagonist that attracted our attention because it has demonstrated high efficacy in multiple cancer models." (PMID 27764791, 2016). "Overlapping Linear Motifs (OLPs) found in the cancer-associated hub proteins (CPs) MYC, APC and MDM2." (PMID 27218803, 2016). "Recently, we have characterized TSPO/MDM2 dual-target ligands and demonstrated that these agents present an attractive multi-modal anti-cancer activity in GBM cells." (PMID 26761214, 2016). "Three MDM2 SNPs(rs937283, rs2270744 and rs769412) have previously been suggested to be positively correlated with cancer." (PMID 27506496, 2016). "MDM2 is oncogenic and is frequently found to be over-expressed in human tumors, suggesting its dysregulation plays an important role in human cancers." (PMID 27023610, 2016). "Substantial heterogeneities were observed for the MDM2 SNP285 polymorphism and risk of cancer under the dominant model (P = 0.043) and allele comparison (P = 0.014), but not under the heterozygous model (P = 0.120)." (PMID 27890964, 2016).
cancer (continued). "We also try to screen for potential small molecule inhibitors that specifically target MDM2 for human cancer therapy, and find several promising natural products, including triptolide." (PMID 27004407, 2016). "In this work, PPI data and de novo motif identification based method (MEME) were used to identify such peptides in three cancer-associated hub proteins—MYC, APC and MDM2." (PMID 27218803, 2016). "Mouse Double Minute 2 (MDM2) promotes cancer cell proliferation and cell cycle progression, inhibits DNA damage response, reduces apoptosis, and stimulates metastasis." (PMID 27105525, 2016). "A series of studies indicate that overexpression of MDM2 in tumors correlates with a poor prognosis for these cancer patients, and high MDM2 expression occurs more frequently in metastatic and recurrent cancers than in primary tumors." (PMID 27004407, 2016). "The promoter demethylation, transcriptional activation and proteolytic degradation have also been reported to contribute to MDM2 overexpression in cancer." (PMID 26840028, 2016). "In the present study, we genotyped MDM2 SNP55 across a large population based study and assessed potential correlations to incidental cancer risk by comparing the genotype status between individuals diagnosed with cancer versus controls." (PMID 27624283, 2016). "Response of cancer cells to nutlin-3 depends on the level of MDM2 and is commonly impaired by overexpression of MDMX." (PMID 26883108, 2016). "The MDM2 SNP285G>C is a newly discovered polymorphism, and this is the first report on the association of this polymorphism and cancer risk." (PMID 27890964, 2016).
cancer (continued). "Clinical trials are currently ongoing to prove clinical efficacy of MDM2 antagonists in cancer therapy." (PMID 26883108, 2016). "MDM2 del1518 was determined in 7,081 Norwegian patients diagnosed with incidental cancers of the breast, colon, prostate or lung as well as 3,749 age-matched healthy individuals." (PMID 27081698, 2016). "The Mdm2 gene is amplified in a considerable proportion of malignant tumors, most notably in sarcomas." (PMID 27183917, 2016). "While in hMSCs, Mdm2 depletion promoted cell differentiation and decreased clonogenic survival in cancer." (PMID 27898034, 2016). "Although the presence of the SNP285C variants seems to antagonize the effect of SNP309G, there are some contradictory studies about MDM2 SNP285 in different types of cancers." (PMID 27890964, 2016). "MDM2 has been reported to be overexpressed via several different molecular mechanisms in many cancer forms." (PMID 27624283, 2016). "Dysregulation of these miRNAs targeting MDM2 has been suggested to be an additional mechanism that contributes to MDM2 overexpression in cancer cells." (PMID 26840028, 2016). "In the last decades, several single nucleotide polymorphisms in the MDM2 as well as the MDM4 loci have been associated with elevated or reduced cancer risk, although data are at variance." (PMID 26867771, 2016). "In MDA-MB-231 cells, the transient transfection of MDM2 siRNA resulted in MDM2 KD, which decreased the cytotoxicity of InuA against cancer cells." (PMID 27105525, 2016). "A single nucleotide polymorphism (T to G) in the mdm2 P2 promoter, mdm2 SNP309, leads to MDM2 overexpression promoting chemotherapy resistant cancers." (PMID 26416444, 2015).